MMP9 (matrix metallopeptidase 9)
Diseases named in the same sentence as MMP9 in open-access papers (continued):
Sharing a sentence is not in itself a finding about the gene and the disease.
cancer (continued). "The expression of MMP-2, MMP-9, and ADAM12m has been shown to have a crucial role in cancer cell invasion and metastasis through promoting degradation of numerous peri-cellular substrates." (PMID 27270327, 2016). "Quantitative real-time polymerase chain reaction (qRT-PCR) analysis showed that transcription of the cancer-associated matrix metalloprotease 2 (MMP2) and MMP9 decreased after silencing of APPL1 and APPL2." (PMID 26583432, 2016). "These networks are interconnected with a subnetwork of genes that are associated with cancer progression, such as COX2, TGFβ, CCL2, CXCL2, MMP9, and MMP13." (PMID 26831400, 2016). "The overexpression of these microRNAs were associated to an oncogenic activity in pancreatic cancer by promoting the expression of MMP-2 and MMP-9, consequently inducing cancer cell invasion, through the down-regulation of TIMP-2." (PMID 27187371, 2016). "As type IV collagen is the major component of the basement membrane, MMP-2 and MMP-9 have crucial roles in the early stages of cancer invasion and metastasis." (PMID 27618887, 2016). "It is well known that macrophages promote cancer cell invasion and metastasis, in part, through production of several factors such as MMP-9 which are responsible for matrix remodeling." (PMID 27793010, 2016). "The levels of endothelial cell marker VE-cadherin, matrix metalloproteinase (MMP)-2 and MMP-9 expression were measured in CD133+ cancer stem cells and xenograft tumors in nude mice injected with CD133+ and CD133– cells, respectively." (PMID 27074560, 2016). "Previous studies have revealed that inhibiting the activity of MMP-2 and MMP-9 reduces cancer cell metastasis." (PMID 26980735, 2016). "We found that ETME-treated cells exhibited downregulated MMP-9 expression in both carcinomas, compared to the control cells." (PMID 27366113, 2016). "The data suggest a cross-talk between N-cadherin and MMP-9 expression in modulating PMA-mediated carcinoma cell invasion." (PMID 27737648, 2016). "We identified a cross-talk between MMP-9 and N-cadherin cleavage involved in the regulation of carcinoma cell invasion, which provides a possible mechanism for MMP-9 in inflammatory-mediated cell invasion via N-cadherin cleavage." (PMID 27737648, 2016). "Given the restricted pattern of N-cadherin expression in carcinoma cells, the cleavage of N-cadherin enhancing cell invasion via increased MMP-9 levels indicated a cross-talk between MMP-9 and N-cadherin in carcinoma cells." (PMID 27737648, 2016). "Applying this peptide on-chip fractionation coupled to MALDI-TOF MS analysis, we can directly profile and investigate the activity of MMP-9 and its cleavage products (peptide fragments) in blood and in cancer cell cultures." (PMID 25788424, 2015). "Among MMPs, MMP2 and MMP9 were found to be overexpressed and mediated higher rates of invasion and metastasis in various types of cancers." (PMID 26084564, 2015). "While a large number of studies have contributed to our understanding of the molecular mechanisms responsible for upregulating MMP-9 gene expression in normal and cancer cells, our knowledge on the signals that suppress MMP-9 expression is much more limited." (PMID 25897433, 2015). "Recently, it was reported that OPN activates the PI3-K/Akt pathway, up-regulates HIF-1alpha via binding to v3 integrins and promotes the degradation of the extracellular matrix through uPA and MMP-9 to mediate cancer cell metastasis." (PMID 26289107, 2015). "In cancer pathology, MMP-2 and MMP-9 are mainly implicated in the formation of new blood vessels through angiogenesis." (PMID 26637202, 2015). "It is reported that ET-1 can stimulate the expression of MMP-9, which contributes to the growth and metastasis of cancer." (PMID 26692905, 2015). "Since MMP-9 plays an important role in cancer invasion, we next detected MMP-9 enzyme activity and expression after PMBPs treatment." (PMID 26539720, 2015).
cancer (continued). "Matrix metalloproteinase 9 (MMP-9) is able to degrade the extracellular matrix and basement membrane leading to cancer cell invasion and metastasis." (PMID 25821815, 2015). "MMP14, MMP2, and MMP9 have all been shown to be important in cancer progression and enriched at the invadopodia." (PMID 25699257, 2015). "It has been demonstrated that ET-1 and MMP-9 are both related to cancer development, progression and metastasis by suppressing apoptosis, and enhancing angiogenesis and mitosis." (PMID 26692905, 2015). "Higher mean levels of IL-6, TNF-α, IL-1β, VEGF, MMP-9 and TF were secreted from healthy monocytes treated with the sera derived from cancer patients DVT compared to those from DVT- (p<0.01)." (PMID 26192925, 2015). "Traditional methods such as IHC, ELISA, immunoblotting and zymography have been used to determine the variation of MMP-9 expression and activity as a result of cancer development." (PMID 25788424, 2015). "Elevated levels of MMP-2 and MMP-9 are often correlated with malignancies of liver, brain, breast, prostate, cervical, ovarian, and other cancers." (PMID 26404213, 2015). "A correlation of MMP9 with mTOR expression in intestinal type cancers was only of weak character and doesn't support mTOR as being the main regulating factor." (PMID 26652716, 2015). "Collectively, these results indicate that expression of NS4B in human hepatocytes induces cancer-related NF-κB target genes including C-myc, Mcl-1, Cyclin D1 and MMP-9 via EOR-Ca2+-ROS-NF-κB pathway." (PMID 25875501, 2015). "As expected, strong correlations between levels of IL-6, TNF-α, IL-1β, VEGF, MMP-9 and TF in plasma from cancer patients DVT+ and DVT- and those released from monocytes of the same patients were observed." (PMID 26192925, 2015). "The activity of active MMP-2 was enhanced when HMF were co-cultured with MDA-MB-231, and active MMP-9 activity was enhanced when HMF were co-cultured with SUM149 or SUM159 cancer cells." (PMID 28721370, 2015). "Matrix metalloproteinase-9 (MMP-9) plays a central role in the invasion and metastasis of various types of cancer cells." (PMID 25670016, 2015). "Matrix metalloproteinase-2 (MMP-2) and −9 (MMP-9) are deeply involved in the pathogenesis of CVDs and cancers." (PMID 26637202, 2015). "MMP2 and MMP9 expression via the activation of NF-κB signaling promotes cancer cell migration and invasiveness." (PMID 26388610, 2015). "Some of them, such as UBE2C, CASP3, CCND1/2, STAT3, JAK2 and MMP-9, have been used as markers of cancer malignancy." (PMID 26603105, 2015). "Here, we show that C3f is specifically cleaved into two peptides (SSATTFRL and LWENGNLLR) by MMP-9 at the L1311–L1312 position, in cancer cell-conditioned culture media." (PMID 25788424, 2015). "The activity of MMPs, particularly MMP-2 and-9, on the degradation of the ECM plays a critical role in the formation of tumors and metastasis, and high MMP-9 levels have been found to correlate with the aggressiveness of cancers." (PMID 25574189, 2015). "In this study, we report that TSP50 have the ability to promote cell invasion and cancer metastasis by increasing MMP9 expression through NF-κB signaling pathway." (PMID 25811800, 2015). "MMP-9 is an important ECM-degrading enzyme that has been reported to be involved in cancer cell invasion and migration." (PMID 25670016, 2015). "FAK also induces the expression of MMP2 and MMP9 accounting for cancer invasion and metastasis via ERK or JNK pathways 31,52,53." (PMID 25351103, 2015). "The MB-downregulated genes include cancer-associated cytokines/chemokines (e.g. CXCL1, CXCL2, CXCL3, CXCL14, IL1A, IL1B, IL6, IL8) and matrix metalloproteinases (MMP1,MMP9)." (PMID 25642713, 2015). "Matrix metalloproteinase-9 (MMP-9) is an important proteolytic enzyme involved in the cancer cell invasion process." (PMID 25875631, 2015).
cancer (continued). "In this study, we found that chrysin-treated cells can decrease cancer invasiveness via inhibiting MMP-9 expression through the suppression of the JNK/c-Jun and ERK/c-Fos signaling pathways." (PMID 25875631, 2015). "Increasing evidence suggests that MMPs, particularly MMP-2 and MMP-9, are upregulated in cancer cells and play a critical role in these processes." (PMID 25927939, 2015). "Among them, MMP-2 (gelatinase A) and MMP-9 (gelatinase B) are known to be strongly correlated with metastatic potential of cancer cells." (PMID 26180515, 2015). "Integrin α3 β1 has also been shown to be important in the metastasis of different types of cancers, by regulating the production of MMP-9." (PMID 25774696, 2015). "MMP-9 enhances cancer progression by regulating angiogenesis, migration, proliferation, and invasion." (PMID 26356670, 2015). "We propose that selective inhibition of MMP9-mediated pathological signaling and matrix proteolysis is a novel therapeutic opportunity in inflammatory conditions such as UC, and in cancers such as CRC." (PMID 25961845, 2015). "Inflammatory cytokines up-regulate various angiogenic factors, such as VEGF and MMP-9, in vascular endothelial cells, cancer cells, and monocytes/macrophages." (PMID 26192925, 2015). "To further confirm that BMP-4 inhibits the expression of MMP-9, we used gremlin, a natural antagonist of BMP-4 which is highly expressed in cancer-associated stromal cells." (PMID 25897433, 2015). "MMP-9 is involved in the degradation of extracellular matrix, a critical step in cancer cell invasion." (PMID 26601108, 2015). "Degradation of extracellular matrix and vascular basement membrane is required for invasion and metastasis of cancer, and MMP9 and MMP2 are critical proteinases that have such a role." (PMID 25811800, 2015). "MDA-MB-231-derived MVs also contain RhoA and RhoC GTPases, which are upregulated in cancer and involved in invasion and metastasis, as well as ADP-ribosylation factor 1 (ARF1), which is associated with MV release and MMP-9 activity within MVs." (PMID 26601108, 2015). "In our experiments, morphine prevented MMP-9 increase and arginase-1 induction in both models of activation (treatment with IL-4 and coculture with cancer cells) in RAW264.7 and BMM cells." (PMID 26078009, 2015). "Wnt/β-catenin has been reported as a key signalling pathway of malignant biological behaviours in many cancers, and it can regulate the expression levels of E-cadherin, MMP-9 and VEGF-C." (PMID 25721268, 2015). "It was shown that although TNF-α increased gelatin degradation by MMP2 and MMP9 in HCT116 cell supernatants, IWR-1significantly reduced the MMP2 and MMP9 activities in the cancer cells, even in the presence of TNF-α-induced cancer cell stimulation." (PMID 26450645, 2015). "MMP-2 and MMP-9 are considered to be prognostic factors in many solid tumors, and also found to promote invasion and metastasis of malignant tumors." (PMID 26404213, 2015). "Several studies have shown that MMP-9 expression is induced by HBx playing an important role in cancer invasion and metastasis in liver cells." (PMID 26446078, 2015). "Increased MMP-2 and MMP-9 activity levels are considered an important mechanism for the increased capacity of cancer cells to traverse the membrane, mimicking invasion and metastasis." (PMID 26043756, 2015). "A large number of studies have contributed to our understanding of the molecular mechanisms responsible for upregulating MMP-9 gene expression in normal and cancer cells." (PMID 25897433, 2015). "It has been known that high levels of MMP-9 expression are important for the invasive phenotype of cancer cells." (PMID 25875631, 2015). "For instance, activation and activity of MMP-9, one of the most widely overexpressed MMP in different types of cancers is enhanced by NGAL (neutrophil gelatinase-associated lipocalin), which additionally protects MMP-9 from degradation." (PMID 25836654, 2015).
cancer (continued). "Previous research has demonstrated that the inhibition of Akt by LY294002 inhibited cancer cell invasion and down-regulated MMP9 expression." (PMID 25638174, 2015). "While HIF-1α is known to regulate proteolytic enzymes such as uPAR, cathepsins, MMP-1, MMP-2, MMP-9 in many cancer types, HIF-2α has directly been involved in membrane bound MT1-MMP in von Hippel-Lindau renal cell carcinoma." (PMID 26305551, 2015). "MMP-2 and MMP-9 can degrade the majority of ECM components and are profoundly associated with the process of cancer invasion and metastasis." (PMID 25633440, 2015). "FAK plays a pivotal role in the regulation of MMP2 and/or MMP9, which are considered to be critical for cancer metastasis and invasion." (PMID 26517117, 2015). "MMPs, mostly MMP2 and MMP9, are known to facilitate cancer cell invasion by degrading extracellular matrix (ECM) proteins, and are thus increased during EMT." (PMID 26450645, 2015). "MMP-9, a downstream target molecule of the MAPK subfamily, is particularly associated with cancer cell invasion." (PMID 25634589, 2015). "Enhanced MMP-2 and MMP-9 activity has been found to contribute to cancer cell migration and invasion." (PMID 26252009, 2015). "MMP-2 and MMP-9 are extracellular metalloproteinases, which play an important role in the degradation of extracellular matrix, thus facilitating cancer cell invasion and migration." (PMID 25854641, 2015). "PEG10 has been shown to promote the expression of MMP-2 and MMP-9 in cancer cells for an enhanced invasiveness." (PMID 26680220, 2015). "Current evidences showed that NF-κB is a major transcriptional factor mediating LMP-1 induced changes of expressions of cancer-related genes including survivin, MMP-9, and EGFR in NPC." (PMID 25861643, 2015). "A growing body of studies suggests that NF-kB activation mediates up-regulation of inflammatory cytokines, angiogenic factors (e.g. CRP, IL-6, TNF-α, IL-1β, VEGF, MMP-9) in cancer." (PMID 26192925, 2015). "Previous reports showed that HuR enhances the expression of different proteins promoting invasion and EMT, including SNAIL, MMP-9, uPA and the uPA receptor; thus HuR appears to be a key factor in cancer progression." (PMID 26136338, 2015). "Matrix metalloproteinase 2 (MMP-2) and MMP-9 are reported to enhance cancer cell invasion via degradation of type IV collagen." (PMID 25402510, 2015). "The importance of NF-κB activity-induced MMP-9 expression in cancer progression has been widely observed in various cancer types." (PMID 26429875, 2015). "Curcumin inhibited vasculogenic mimicry, decreased cell migration and MMP-9 (matrix metalloproteinase-9) production of the cancer cells." (PMID 25566531, 2014). "In the decade that has passed since the abandonment of early generation MMP inhibitors as experimental cancer drugs, many novel and innovative approaches to more selective MMP9 inhibition have emerged." (PMID 24811362, 2014). "In our study, OSEO showed strong anti-inflammatory activity by suppressing the expression of MMP-9 in LPS-induced inflammatory cells, which in turn triggered the prevention of cancer cell migration." (PMID 25431779, 2014). "IL-6 and MMP-9 promote invasion and metastasis of cancer cells via accelerating ECM degradation, inflammation, angiogenesis and proliferation." (PMID 25058006, 2014). "Among the MMP family members, MMP-2 and MMP-9 are molecules important for cancer invasion, and have been shown to be highly expressed in cancer cells." (PMID 25202430, 2014). "In this report, we sought to elucidate the WAVE3-mediated signaling events that lead to the production and activation of MMP9 in cancer cells." (PMID 25329315, 2014). "This factor is also activated in several other cancers and results in the increased regulation and activation of matrix metalloproteinase-9 (MMP-9), which is responsible for the destruction of extracellular matrix and basal membranes." (PMID 24738058, 2014).
cancer (continued). "The metalloproteinases MMP-2 and MMP-9 are involved in the regulation of cancer cell migration and metastasis, while the transcription factor EGR-1 participates in the regulation of cell proliferation, migration and apoptosis." (PMID 25260978, 2014). "Why should the cell from which MMP9 is derived be important for its role in cancer progression or for its prognostic significance?" (PMID 24811362, 2014). "Indigenous stromal cells surrounding cancer cells in luminal A and B revealed only faint levels of MMP-9 expression." (PMID 25151367, 2014). "Certain previous studies have shown that EGF stimulates the expression of MMP1 and MMP9 in several cancers." (PMID 24765152, 2014). "Most published data on MMP-2 and MMP-9 address the role of these proteins in encouraging the aggressiveness of cancers." (PMID 25097794, 2014). "Mean serum MMP9 concentration in malignant tumors was (402.3±441.8pg/ml) higher than benign tumors (354.3±218.7 pg/ml) but the difference was not significant (p= 0.9)." (PMID 25469360, 2014). "On-going studies are investigating the value of the pro-MMP-9/NGAL complex as a marker of disease status in cancer." (PMID 24713998, 2014). "Previous reports have described that intercellular adhesion molecule-1 (ICAM-1) and matrix metalloproteinase 9 (MMP-9) are involved in cancer cell adhesion, invasion, and migration, which contribute to cancer metastasis." (PMID 24901215, 2014). "MMP-9 is capable of regulating the release of VEGF, so VEGF is also highly expressed in cancer cells with high expression of MMP-9, both of which are related with lymphatic metastasis." (PMID 24829764, 2014). "Our and other laboratories have reported that a specific inhibitor for EGFR efficiently blocked EGF-induced activation of MMP9 and reduced cancer invasiveness." (PMID 25380967, 2014). "TGF-β1 also increases the expression of fetal liver kinase-1 (Flk-1), a major VEGF receptor, and TGF-β1 and VEGF stimulate MMP-9 expression, respectively, thus increasing the invasiveness of cancer cells." (PMID 24578639, 2014). "We show that WAVE3-mediated modulation of NFκB is required for invadopodia formation as well as MMP9 expression and activity that are needed for cancer cells to degrade the ECM." (PMID 25329315, 2014). "Mean serum MMP9 concentration in malignant tumors was (402.3±441.8pg/ml) higher than benign tumors (354.3±218.7 pg/ml) but the difference was not statistically significant (p= 0.9)." (PMID 25469360, 2014). "Nevertheless, the level of MMP-9 in the cytoplasm of cancer cells always exceeded that found in adjacent stromal cells." (PMID 25151367, 2014). "A similar interaction induces gelatinase B/MMP-9 expression in cancer cells, promoting dissemination and metastasis to bone." (PMID 24473089, 2014). "More importantly, the MMP secretion was Notch dependent because inhibition of the Notch effector Hey1 decreased both MMP2 and MMP9, which eventually decreased cancer cell invasion." (PMID 24931473, 2014). "Matrix metalloprotease-9 (MMP-9), one of member of the matrix metalloprotease family, is essential for the cancer cell metastasis and migration, which are the major characteristics of malignant tumors and the most important reasons causing death." (PMID 24603556, 2014). "MMP-9 correlates with malignant phenotypes in various types of cancer and can be activated by a variety of stimuli such as cytokines and phorbol myristate acetate (PMA) during varied pathological processes." (PMID 25174454, 2014). "MMP-2 and MMP-9 are zinc-dependent endopeptidases that play critical roles in cancer progression and metastasis." (PMID 24581171, 2014). "These evidences further support the multiple roles of MMP-9 observed in cancer and summarized below." (PMID 24713998, 2014). "Matrix metalloproteinase (MMP)-9 secreted from cancer stroma populated by CAFs is a prerequisite for cancer angiogenesis and metastasis." (PMID 24586907, 2014).